FOXO3 (forkhead box O3)
Diseases named in the same sentence as FOXO3 in open-access papers (continued):
Sharing a sentence is not in itself a finding about the gene and the disease.
breast carcinoma (continued). "Data suggests the prognostic significance and the tumour-suppressive role of FOXO3 in breast cancer cases studied in India." (PMID 36727057, 2022). "SIRT6 promotes breast cancer by regulating the acetylation and sensitivity to lapatinib of Forkhead box protein O3 (FoxO3)." (PMID 35172823, 2022). "The studies focused on the correlation of expression, cellular localization, and epigenetic modulation of FOXO3 in breast cancer with the clinical staging and other clinicopathological parameters in the Indian population." (PMID 36727057, 2022). "Studies have shown that through in vivo and in vitro experiments, circ-Foxo3 is a potential tumor suppressor in breast cancer; it works by using miRNA sponge." (PMID 35419056, 2022). "Correlation analysis between FOXO3 methylation and FOXO3 protein expression in stratification by various clinical characteristics of Breast cancer patients from North India." (PMID 36727057, 2022). "We investigated the FOXO3 gene status in cases of Indian female breast cancer (n=127) by thorough evaluation of its corresponding expression (via Immunohistochemistry), mRNA (via Real-Time PCR), and epigenetic modifications through MS-PCR." (PMID 36727057, 2022). "We examined the FOXO3 expression levels in breast cancer samples by analyzing mRNA and protein expression along with its clinicopathological parameters." (PMID 36727057, 2022). "Correlation study of FOXO3 Promoter Methylation status with clinical parameters of Breast Cancer Patients." (PMID 36727057, 2022). "The expression of a transcription factor named FOXO3a (Forkhead box O3) is enhanced by apigenin in breast cancer patients, which downregulates AKT signal transduction." (PMID 35807549, 2022). "As per the previous studies on breast cancer tissue and cell lines, our data also demonstrated that breast cancer tissue exhibits higher levels of FOXO3 promoter methylation when compared to normal tissue." (PMID 36727057, 2022). "In MCF-7 breast cancer cells, oxidative stress activates the transcription factor forkhead box O3 (FOXO3), stimulating the transcription of LC3 and adenovirus E1B 19-kDa-interacting protein 3 (BNIP3), which are involved in autophagy." (PMID 35530337, 2022). "In recent years, many studies had shown that miR-155 played a regulatory role in lung cancer, kidney cancer, breast cancer, colorectal cancer, and other tumors by targeting Forkhead box O3 (FOXO3)." (PMID 35434143, 2022). "Recently, sumoylation (Lys 527 and Lys633) was associated with the regulation of FOXK2 activity, and its role in mediating the cytotoxic response to paclitaxel through the tumor suppressor FOXO3 in breast cancer cells was recently reported." (PMID 36172141, 2022). "TF motif analyses further identified COUP-TFII and FOXO3, both of which are known TFs that regulate gene expression of multiple pathways in breast cancer." (PMID 35137163, 2022). "Phosphorylation of FOXO3 on Ser-7 by p38 is essential for its nuclear relocalization in response to treatment in breast carcinoma cells." (PMID 36531208, 2022). "While probing the FOXO3 promoter methylation levels in breast cancer sample, 57.4% (73/127) cases showed hypermethylation in their promoter region." (PMID 36727057, 2022). "FOXO3, known as a tumor suppressor, acts via decreasing cell proliferation and metastasis and increasing apoptosis in various cancers, including breast cancer; however, the role of HIPK3 has received less attention." (PMID 36132137, 2022). "For example, loss of FOXO3 upregulates Snail and induces EMT in clear cell carcinoma, whereas in breast cancer cells, increased expression has the opposite effect." (PMID 35008549, 2021).
breast carcinoma (continued). "In consistency with our study, geminin‐associated HDAC3 has been proposed to deacetylate FOXO3 to inhibit its transcriptional activity, thus inhibiting downstream FOXO3 target Dicer, an essential RNase to inhibit metastasis of breast cancer cell." (PMID 33655712, 2021). "Currently, a growing body of evidence demonstrates that Foxo3 aberrantly expresses in several cancers, including breast cancer, lung cancer, and esophageal squamous cell cancer progression." (PMID 34555810, 2021). "Under the dual role of circ-Foxo3, the progression of breast cancer was inhibited via inducing cell apoptosis." (PMID 33833780, 2021). "Mounting evidence has shown the abnormal expression of circ-Foxo3 in numerous human cancers, including breast cancer (BC), lung cancer, glioma, ESCC, leukemia, gastric cancer (GC), bladder cancer, prostate cancer (PCa) and OC." (PMID 33833780, 2021). "A recent study demonstrated that geminin is aberrantly overexpressed in breast cancer tissues and promotes tumor invasionand metastasis by suppressing FoxO3-mediated transactivation of Dicer." (PMID 34874226, 2021). "The prognostic significance of these three parameters persisted in multivariate analysis, indicating that FOXO3 protein expression is an independent prognostic factor in breast cancer." (PMID 32332845, 2020). "We used the GEPIA, UALCAN and KM‐plotter databases to investigate the expression of FOXO3 in human breast cancer and adjacent normal tissues, and its correlation with survival." (PMID 32100957, 2020). "FOXO3 knockdown in pancreatic ductal carcinoma, glioblastoma, and breast cancer xenograft experiments can inhibit cancer progression and metastasis." (PMID 32629884, 2020). "In our study, we found weak correlations between FOXO1 and FOXO3 RNA and protein expressions in breast cancer." (PMID 32332845, 2020). "p38 MAPK has been shown to phosphorylate FOXO3 on Ser7 to mediate nuclear localisation and senescence in response to doxorubicin-induced DNA damages in breast cancer." (PMID 32372224, 2020). "It is noted that DNMT1, DNMT3a, and DNMT3b are all recruited to the FOXO3 promoter in breast cancer HCC70 and MDA-MB-468 cells." (PMID 31296961, 2020). "Polyphenol epigallocatechin-3-gallate in green tea can upregulate FOXO3 and suppress breast cancer metastasis." (PMID 32372224, 2020). "Consistently, we have also shown recently that PERK also promotes resistance to ER stress and cytotoxic drugs through the repression of FOXO3 by promoting AKT activation in breast cancer cells." (PMID 32615282, 2020). "We performed an analysis of FOXO3 expression in breast cancer tissues by using GEPIA and UALCAN databases." (PMID 32100957, 2020). "Further protein expression studies based on larger series of breast cancers are necessary to determine the precise role of FOXO3 protein in the various subtypes of breast cancer." (PMID 32332845, 2020). "To investigate in more detail the role of FOXO1 and FOXO3 genes in breast cancer, we also performed a log rank test to analyse the relationship between FOXO1 and FOXO3 protein expressions and metastasis-free survival (MFS)." (PMID 32332845, 2020). "Overexpression of FOXO1 and FOXO3 proteins in breast cancer has been shown to inhibit the growth of breast cancer cells." (PMID 32332845, 2020). "FOXO3 has also been reported to repress the expression of the potent angiogenic growth factor VEGF at the promoter level in breast cancer." (PMID 32372224, 2020). "Other studies also report that FOXO3 nuclear localization correlates with less frequent metastatic formation and better prognosis in luminal-like breast cancer." (PMID 32629884, 2020). "Altogether, these results strongly suggest that FOXO1 and FOXO3 proteins act as tumor suppressors in breast cancer." (PMID 32332845, 2020). "FOXK2 has also been found to regulate FOXO3 expression at the transcriptional level to mediate the cytotoxic effects of epirubicin and paclitaxel in breast cancer." (PMID 32372224, 2020).
breast carcinoma (continued). "FOXO3 suppresses VEGF expression in breast cancer, and a cDNA microarray study in a colon carcinoma cell line provided evidence that it can repress the expression of Myc target genes." (PMID 32629884, 2020). "Mechanistically, overexpression of CHP2 activated AKT signaling and suppressed the transactivation of the forkhead box O3 (FOXO3/FOXO3a) transcription factor in breast cancer." (PMID 32256214, 2020). "In breast cancer FOXO3 modulates tumor progression by promoting cell invasion via the induction of matrix metalloproteinases and in pancreatic cancer active FOXO3 correlates with poor prognosis as it acts as an essential regulator of CD44+ stem cells." (PMID 31591479, 2020). "EP300 and SIRT1/6 also co-regulate the cytotoxic function of the EGFR/HER2 inhibitor lapatinib through modulating FOXO3 acetylation and activity in breast cancer." (PMID 32372224, 2020). "Immunohistochemical staining results also show that FOXO3 expression correlates positively with SIRT6/1 levels in different breast cancer subtypes." (PMID 31357743, 2019). "FoxO3 has been reported to transcriptionally activate Dicer, which in turn regulates miRNA maturation and breast cancer metastasis." (PMID 31685800, 2019). "Taken together, these results provide strong evidence that FOXO3 regulates PERK expression in human breast cancer." (PMID 31312024, 2019). "Re-expression of LINC01355 suppresses the growth and tumorigenesis of breast cancer cells, which involves the stabilization of FOXO3 and enhancement of FOXO3-mediated transrepression of CCND1." (PMID 31243265, 2019). "In summary, in the present study we identify a role of EP300-mediated FOXO3 acetylation in the regulation of lapatinib sensitivity in breast cancer." (PMID 31357743, 2019). "Another well-known circular transcript from forkhead box O3 (circ-Foxo3), which is suppressed in breast cancer and non-small cell lung cancer, can bind to some transcription factors." (PMID 30774645, 2019). "FOXO3 was one of the first FOXO factors recognized as a tumor suppressor in human breast cancer since its absence correlated with poor patient survival." (PMID 31303978, 2019). "Previous work has also suggested that FOXO3 mediates the cytotoxicity of Lapatinib in breast cancer." (PMID 31727006, 2019). "HMGN2 is an anti-tumor effector molecule of CD8+T cells, FOXO3 is a core tumor suppressor in breast cancer; downregulation of PPP2R5E is a common event in acute myeloid leukemia." (PMID 31540229, 2019). "LINC01355-mediated inhibition of breast cancer cell proliferation and clonogenicity were reversed by knockdown of FOXO3." (PMID 31243265, 2019). "LINC01355 acts as a tumor suppressor in breast cancer, which is ascribed to enhancement of FOXO3-mediated transcriptional repression of CCND1." (PMID 31243265, 2019). "In agreement, constitutively nuclear FOXO3 localisation indicates deregulated FOXO3 function and also predicts poor survival in breast cancer samples." (PMID 31312024, 2019). "With this background in mind, the present study aimed to analyze the effect of the FOXO3 and p27Kip1 genes on the control of the breast cancer MDA-MB-231 cell line, using a bidirectional survivin promoter." (PMID 31294654, 2019). "Other studies also show that cytoplasmic FOXO3 is also a favourable independent prognostic factor in breast cancer." (PMID 31312024, 2019). "ER promotes estrogen-dependent breast cancer cell proliferation and tumorigenesis, whereas FOXO3 suppresses these effects." (PMID 31439835, 2019). "Conversely, chemotherapeutic drugs and PERK inhibitors can activate FOXO3 via inhibiting PERK-AKT axis in breast cancer cells." (PMID 31312024, 2019). "The fact that there is a strong and significant correlation between PERK and FOXO3 expression in the breast cancer patient samples suggest that this FOXO3-PERK regulatory axis is preserved in most breast cancers." (PMID 31312024, 2019).
breast carcinoma (continued). "FOXO3 promotes breast cancer cell invasion through the induction of MMP-9 and MMP-13 and has further been associated with MMP-9 activity and elevated invasion capacity in glioma, and with increased cell migration and invasion in gastric and colorectal cancer." (PMID 31861249, 2019). "More recently, an alternative mechanism played by FoxO1 and FoxO3 in lapatinib response of breast cancer cells has been reported." (PMID 30646603, 2019). "Omics studies have revealed several pathways and genes related to breast cancer, such as p27Kip1 and forkhead box O3 (FOXO3)." (PMID 31294654, 2019). "In agreement, cytoplasmic FOXO3 is also a favourable independent prognostic factor in breast cancer." (PMID 31312024, 2019). "Collectively, our results suggest the involvement of FOXO3 acetylation in regulating lapatinib sensitivity of HER2-positive breast cancers." (PMID 31357743, 2019). "In the present study we analyzed the effect of simultaneous FOXO3 silencing and p27Kip1 activation on breast cancer cell survival and the potential targets of these changes in cancer molecular pathways." (PMID 31294654, 2019). "Together, these results suggest a significant role of EP300-mediated acetylation of FOXO3 in regulating HER2-positive breast cancer cell survival and their lapatinib sensitivity." (PMID 31357743, 2019). "The FOXO3 transcription factor has been shown to mediate the cytotoxic effects of chemotherapeutic agents in breast cancer through promoting the expression of downstream transcriptional targets involved in proliferative arrest and cell death." (PMID 29540677, 2018). "In breast cancer, miR-221-222 targets FOXO3 and is involved in the promotion of an aggressive breast CSC-related phenotype and EMT." (PMID 29180117, 2018). "In concordance, there is a positive correlation between ERα and FOXM1, and an inverse correlation between ERα and FOXO3 in breast cancer patients." (PMID 29180117, 2018). "Circ-Foxo3 is downregulated in breast cancer specimens compared to the adjacent normal tissue, and nanoparticle-mediated delivery of a circ-Foxo3 plasmid in xenografts resulted in smaller tumors displaying a high percentage of TUNEL-positive cells." (PMID 29570632, 2018). "Previous studies showed that IKKβ promoted the development of breast carcinoma by phosphorylating two tumor suppressor factors, forkhead box O3a (FOXO3a) and tuberous sclerosis complex 1 (TSC1)." (PMID 30154412, 2018). "Over-expression of Foxo3P, Foxo3 and circ-Foxo3 in a breast cancer cell line decreased cell proliferation and induced extensive cell death due to apoptosis in tumors formed by the same cell line in nude mice." (PMID 30018188, 2018). "The mechanism by which Erk activation promotes breast cancer progression via inhibition of FOXO3 expression has also been shown to be through MDM2-mediated degradation." (PMID 29915392, 2018). "Here, we report that FOXK2 is modified by SUMOylation and overexpression of a SUMOylation-defective form of FOXK2 prevents endogenous FOXK2-mediated induction of FOXO3 expression and confers paclitaxel resistance to drug-sensitive breast cancer cells." (PMID 29540677, 2018). "The prevalence of somatic FOXO3 aberrations is 41%, 9%, and 0.5% in breast cancer, prostate cancer, and CRCs in humans, it has been implicated in liver and brain tumors in mice and is a negative regulator of Ras/MAPK." (PMID 29301589, 2018). "A recent study demonstrated that casticin treatment induced apoptosis in breast cancer cells via the activation of forkhead box O3 (FOXO3a) and the repression of forkhead box protein M1 (FOXM1)." (PMID 30401729, 2018). "Overexpression of circ-Foxo3 in the MDA-MB-231 breast cancer cell line significantly reduces cell proliferation in vitro." (PMID 30064463, 2018). "By contrast, in breast cancer, a positive regulation of FOXO3 exerted by the EGCG has been described." (PMID 30563268, 2018).
breast carcinoma (continued). "The capacity of circ-Foxo3 in inducing cell apoptosis and inhibit progression of breast cancer makes it a promising therapeutic target of breast cancer." (PMID 30157902, 2018). "As CDK2 is associated with multiple cancers, like breast cancer, colorectal cancer, non-small cell lung cancer (NSCLC), hence, circ-Foxo3 also carry out functions in cancers above by forming circ-Foxo3-p21-CDK2 ternary complex." (PMID 28969093, 2017). "Paclitaxel, which is also used for the treatment of breast cancer, was shown to stimulate apoptosis via FOXO3-induced Bim expression." (PMID 29299162, 2017). "Controversially to this suggestion, it was published that FOXO3 is activated downstream of HIF-1α in fibroblasts as well as in breast cancer cells." (PMID 29250065, 2017). "IKKβ also promotes breast cancer through the phosphorylation of forkhead box O3 (FOXO3a), which triggers its cytoplasmic export and proteasomal degradation, resulting in increased proliferation and tumorigenesis." (PMID 28587092, 2017). "Circ-Seq analysis of circRNAs, has confirmed that circ-Foxo3 is also downregulated in breast cancer cell lines and breast cancer tissues when compared with noncancerous cell lines or normal tissues." (PMID 28969099, 2017). "In human breast cancer cell lines, Foxo3P and circ-Foxo3 promoted the translation of Foxo3 mRNA by binding regulatory miRNAs and increased Foxo3-mediated apoptosis." (PMID 29349062, 2017). "Overexpression of circ-Foxo3 in the breast cancer cell line, MDA-MB-231, significantly reduced proliferation and cell survival in vitro." (PMID 28969099, 2017). "The results suggest that the tumour suppressive role of BRCA1 is partially achieved by regulating FOXO3 expression in breast cancer." (PMID 27043660, 2016). "Consistently, high FOXO3 and EZH2 mRNA levels were significantly associated with good and poor prognosis in breast cancer, respectively." (PMID 27043660, 2016). "In breast cancer stem-like cells, FoxO3 activation by Akt inhibition reduced stemness and triggered cell death; overexpression of dominant-negative FoxO3 retained stem cell marker expression and viability." (PMID 27448972, 2016). "The association of both FOXO3 and EZH2 mRNA levels in survival analyses provides further evidence for the involvement of both genes in breast cancer progression." (PMID 27043660, 2016). "The finding that overexpression of FOXO3 mRNA levels is a good prognostic factor in breast cancer further supports the importance of FOXO3 regulation at the transcriptional level in breast cancer development." (PMID 27043660, 2016). "Our data on NB tumors support other studies from e.g. leukemia and breast cancer, where the FOXO3 “death program” was perverted into a “tumor longevity program” with increased death resistance and invasion." (PMID 27769056, 2016). "We found that ergosterol-mediated suppression of breast cancer cell viability occurred through apoptosis and that ergosterol up-regulated expression of the tumor suppressor Foxo3." (PMID 26098777, 2015). "Our data showed that Foxo3 was up-regulated after ergosterol treatment in breast cancer cells (MDA-MB-231) when the cells underwent apoptosis." (PMID 26098777, 2015). "MiR-96 has been reported to exert an oncogenic effect in non-small cell lung cancer, esophageal cancer, breast cancer, hepatocellular carcinoma, and prostate cancer, respectively by inhibiting the expression of FOXO3, RECK, FOXO3a and FOXO1." (PMID 26582573, 2015). "Constitutive AKT activation is frequently correlated with cytoplasmic Forkhead box O3a (FOXO3a) and decreased patient survival in breast cancer and other malignancies." (PMID 25583261, 2015). "MCF7 breast cancer cells were transfected with GFP-fused Forkhead box O3 (FOXO3) as a reporter to assess localization in response to estrogen stimulation." (PMID 26470790, 2015).